BAG6 (BAG cochaperone 6)
Description:
ATP-independent molecular chaperone preventing the aggregation of misfolded and hydrophobic patches-containing proteins. Functions as part of a cytosolic protein quality control complex, the BAG6/BAT3 complex, which maintains these client proteins in a soluble state and participates in their proper delivery to the endoplasmic reticulum or alternatively can promote their sorting to the proteasome where they undergo degradation. The BAG6/BAT3 complex is involved in the post-translational delivery of tail-anchored/type II transmembrane proteins to the endoplasmic reticulum membrane. Recruited to ribosomes, it interacts with the transmembrane region of newly synthesized tail-anchored proteins and together with SGTA and ASNA1 mediates their delivery to the endoplasmic reticulum. Client proteins that cannot be properly delivered to the endoplasmic reticulum are ubiquitinated by RNF126, an E3 ubiquitin-protein ligase associated with BAG6 and are sorted to the proteasome. SGTA which prevents the recruitment of RNF126 to BAG6 may negatively regulate the ubiquitination and the proteasomal degradation of client proteins. Similarly, the BAG6/BAT3 complex also functions as a sorting platform for proteins of the secretory pathway that are mislocalized to the cytosol either delivering them to the proteasome for degradation or to the endoplasmic reticulum. The BAG6/BAT3 complex also plays a role in the endoplasmic reticulum-associated degradation (ERAD), a quality control mechanism that eliminates unwanted proteins of the endoplasmic reticulum through their retrotranslocation to the cytosol and their targeting to the proteasome. It maintains these retrotranslocated proteins in an unfolded yet soluble state condition in the cytosol to ensure their proper delivery to the proteasome. BAG6 is also required for selective ubiquitin-mediated degradation of defective nascent chain polypeptides by the proteasome. In this context, it may participate in the production of antigenic peptides and play a role in antigen presentation in immune response (By similarity). BAG6 is also involved in endoplasmic reticulum stress-induced pre-emptive quality control, a mechanism that selectively attenuates the translocation of newly synthesized proteins into the endoplasmic reticulum and reroutes them to the cytosol for proteasomal degradation. BAG6 may ensure the proper degradation of these proteins and thereby protects the endoplasmic reticulum from protein overload upon stress. By inhibiting the polyubiquitination and subsequent proteasomal degradation of HSPA2 it may also play a role in the assembly of the synaptonemal complex during spermatogenesis (By similarity). Also positively regulates apoptosis by interacting with and stabilizing the proapoptotic factor AIFM1 (By similarity). By controlling the steady-state expression of the IGF1R receptor, indirectly regulates the insulin-like growth factor receptor signaling pathway. When nuclear, may also act as a component of some chromatin regulator complex that regulates histone 3 'Lys-4' dimethylation (H3K4me2). Released extracellularly via exosomes, it is a ligand of the natural killer/NK cells receptor NCR3 and stimulates NK cells cytotoxicity. It may thereby trigger NK cells cytotoxicity against neighboring tumor cells and immature myeloid dendritic cells (DC). Mediates ricin-induced apoptosis.
Synonyms: BAG-6; BAT3; G3; D6S52E; Scythe
Tractability: Small molecule: a structure with a bound ligand is known. Antibody: UniProt places it where antibodies can reach, with high confidence; its Gene Ontology location is reachable by antibodies, with medium confidence. PROTAC: UniProt records ubiquitination sites on it; ubiquitination databases record sites on it; its protein half-life has been measured.
Safety:
Unwanted effects reported when the protein is acted on. In parentheses: how it was acted on, where the effect was seen, and who reports it.
Stevens-Johnson syndrome (source: ClinPGx)
Gene: Protein-coding gene on chromosome 6 (31,638,544 to 31,652,747, reverse strand). Ensembl gene ENSG00000204463.
Subcellular location: Cytoplasm, cytosol; Nucleus; Secreted, extracellular exosome
Subcellular location (Human Protein Atlas): Nucleoplasm; Cytosol; Vesicles
Pathways (Reactome):
Protein localization: Insertion of tail-anchored proteins into the endoplasmic reticulum membrane
Gene Ontology:
Molecular function: misfolded protein binding; molecular adaptor activity; molecular function activator activity; protein binding; protein carrier chaperone; receptor ligand activity; ribosome binding; signaling receptor binding; ubiquitin protein ligase binding; ubiquitin-specific protease binding; polyubiquitin modification-dependent protein binding; proteasome binding; Hsp70 protein binding
Biological process: apoptotic process; endoplasmic reticulum stress-induced pre-emptive quality control; ERAD pathway; immune response-activating cell surface receptor signaling pathway; internal peptidyl-lysine acetylation; natural killer cell activation; NK T cell activation; positive regulation of ERAD pathway; post-translational protein targeting to endoplasmic reticulum membrane; proteasomal protein catabolic process; regulation of protein stability; tail-anchored membrane protein insertion into ER membrane; ubiquitin-dependent protein catabolic process; brain development; intrinsic apoptotic signaling pathway in response to endoplasmic reticulum stress; kidney development; lung development; negative regulation of proteasomal ubiquitin-dependent protein catabolic process; negative regulation of proteolysis; protein stabilization; regulation of embryonic development; spermatogenesis; synaptonemal complex assembly; proteasome-mediated ubiquitin-dependent protein catabolic process; and 1 more
Cellular component: BAT3 complex; cytoplasm; cytosol; extracellular exosome; membrane; nucleoplasm; nucleus; extracellular region
Genetic constraint (gnomAD): Loss-of-function variants: 22 observed, 118.63 expected, observed/expected ratio (o/e) 0.19, 90% interval 0.13 to 0.26. The upper end of that interval is the gene's LOEUF score, 0.26, which puts it in group 1 of 6, group 1 being the genes least tolerant of losing a copy. Missense variants: 1,207 observed, 1,547 expected, observed/expected ratio (o/e) 0.78, 90% interval 0.74 to 0.82. Synonymous variants: 578 observed, 594.49 expected, observed/expected ratio (o/e) 0.97, 90% interval 0.91 to 1.04.
Homologues: Orthologues: chimpanzee BAG6 (99% identical), macaque BAG6 (97% identical), dog BAG6 (96% identical), pig BAG6 (96% identical), guinea pig BAG6 (95% identical), rabbit BAG6 (95% identical), rat Bag6 (94% identical), mouse Bag6 (92% identical), tropical clawed frog bag6 (54% identical), zebrafish bag6l (50% identical), zebrafish bag6 (48% identical), Drosophila melanogaster CG7546 (23% identical), and 1 more.
Diseases named in the same sentence as BAG6 in open-access papers:
BAG6 is named in the same sentence as 73 diseases in open-access papers, as found by Europe PMC text mining. Sharing a sentence is not in itself a finding about the gene and the disease. The quoted sentences say what the papers report.
melanoma (12 papers, 2012 to 2025). A malignant, usually aggressive tumor composed of atypical, neoplastic melanocytes. "Intriguingly, EVs derived from BAG6-deficient and BAG6-containing melanoma cells differ significantly in their protein and mRNA cargo, and mice conditioned with these EVs develop distinct molecular changes in their lungs." (PMID 33348923, 2020). "A recent mouse model of experimental melanoma metastasis identified the chaperone Bcl-2-associated anthogene 6 (BAG6) as a molecular toggle that determines the secretion of EVs with anti- or pro-metastatic cargo." (PMID 33348923, 2020). "This is initially based on the finding that EVs from BAG6-proficient and BAG6-deficient melanoma cells were characterized by distinct protein and mRNA cargo loading." (PMID 31534536, 2019). "Mutations in the BAG6 gene, which we consider a novel tumor suppessor gene, are rarely detected in melanoma and other tumors, but we investigated a specific mutation described in a melanoma and a pancreatic cancer patient (uniprot/BAG6_HUMAN, stop gained BAG6 R786*)." (PMID 31534536, 2019). "Activation of the innate pattern recognition receptor RIG-1 in human melanoma cell lines induced the release of EVs enriched for BAG6, a ligand for NKp30, another NK-activating receptor." (PMID 36081494, 2022). "Instead, BAG6 promotes generation and cargo-loading of immune-stimulatory EVs released by stressed melanoma cells, thus explaining their immune-stimulatory function in mice lacking functional NKp30." (PMID 36081494, 2022). "RIG-I stimulation in melanoma cells induced the release of extracellular vesicles, which expressed enhanced levels of the inducible NKp30 ligand (BAG6) on their surface." (PMID 33121210, 2020). "The interaction between BAG6 and the NK p30 receptor on NK cells triggered NK cell-mediated lysis of melanoma cells." (PMID 33121210, 2020). "In line with tumor-suppressing activity, we observed that a rare BAG6 mutation identified in a melanoma and pancreatic cancer patient encoding a truncated protein had dominant negative activity affecting the acetyltransferase activity of CBP/p300/BAG6." (PMID 31534536, 2019). "Nuclear BAG6, relying on its P(S/T)AP motif, binds to TSG101 (an ESCRT protein complex that remodels the inner membrane, leading to membrane budding and vesicle formation), promoting the release of BAG6+ vesicles with anti-metastatic activity and inhibiting melanoma cell lung metastasis." (PMID 39766882, 2024). "Using an experimental metastasis melanoma model we show that BAG6 is indispensable for the formation of anti-metastatic EVs, which are characterized by the presence of TIMP3, an inhibitor of metalloproteinases involved in the re-modelling of the extracellular matrix." (PMID 31534536, 2019). "Extracellular vesicles from melanoma cells increase IFN‐γ secretion, enhancing NKp30 ligand (BAG6, BAT3) expression on their surface, which activates cytotoxic NK cells and increases their tumoricidal activity." (PMID 39513664, 2024). "The inducibility of BAG6 on EVs in response to hypoxia as a melanoma-relevant stress factor has not been analyzed before." (PMID 31534536, 2019).
lung carcinoma (10 papers, 2010 to 2025). "In the lung cancer risk model, BAG6 rs1077393, the most important SNP, remained in the top five important SNPs in risk models for people under the age of 60 and people with family history." (PMID 35499292, 2022). "After FDR adjustment, TYMS rs3819102 and BAG6 rs1077393 were significantly associated with lung cancer risk (p < 0.05)." (PMID 35499292, 2022). "Polymorphism in BAG6 (rs3117582) was reported to have strong evidence of association with lung cancer risk among Caucasians in a meta‐analysis." (PMID 35499292, 2022). "FAM46A protein interacts with the BCL2-Associated Athanogene 6 (BAG6) protein which has been reported to modify risk of lung cancer." (PMID 25884493, 2015). "Our results also corroborate the previous findings that BAG6 gene is associated with lung cancer and suggest gene-dosage association of the BAG rs3117582 SNP with NSCLC." (PMID 25884493, 2015). "Previous reports have shown that SNPs in BAG6 gene (rs1052486 and rs3117582) conferred susceptibility to lung cancer." (PMID 25884493, 2015). "For the BAG6 rs3117582 polymorphism we found a gene-dosage increased risk for lung cancer associated with the C allele of BAG6 rs3117582 SNP in the Norwegian subjects." (PMID 25884493, 2015). "BAG6 rs1077393 was found to decrease the risk of developing lung cancer." (PMID 35499292, 2022). "In addition, we analyzed for the association of a BAG6 SNP to validate its previous reported association with lung cancer." (PMID 25884493, 2015). "We found also that BAG6 rs3117582 SNP was associated with non small cell lung cancer in the Norwegian subjects and the combined Croatian-Norwegian subjects corroborating the earlier finding that BAG6 rs3117582 SNP was associated with lung cancer in Europeans." (PMID 25884493, 2015). "BAG6 rs1077393 was the most important predictor among all SNPs in the lung cancer prediction XGBoost model, followed by TERT rs2735845 and CAMKK1 rs7214723." (PMID 35499292, 2022). "In both XGBoost‐based lung cancer risk and SCC risk prediction models, the most important SNP was in BAG6." (PMID 35499292, 2022). "Bag6 appears to be a negative regulator in the innate immune system of non-small cell lung cancer patients and a risk factor for lung cancer, even in early non-smoker lung adenocarcinoma patients." (PMID 39172905, 2024). "However, we found that, regardless of EGFR mutation status, high pleural BAG6 levels were associated with poorer overall survival in lung cancer patients with MPE regardless of EGFR status." (PMID 40959273, 2025). "Given wide-stretched linkage disequilibrium to the area APOM/BAG6/MSH5, there is currently simply not enough information or evidence to conclude whether the potential pleiotropy of lung cancer and systemic lupus erythematosus is spurious, biological, or mediated." (PMID 28273134, 2017).
chronic lymphocytic leukemia (7 papers, 2016 to 2022). "Nevertheless, it has been shown that the level of soluble ligands for NKp30—BAG6/BAT3 in the plasma of patients with chronic lymphocytic leukemia is positively correlated with the stage of the disease." (PMID 34768814, 2021). "Regarding hematological malignancies, in chronic lymphocytic leukemia (CLL) patients, high plasma levels of soluble BAG6 have been associated with advanced disease stages; in contrast, NK cells were activated by BAG6 presented on the surface of exosomes." (PMID 31623224, 2019). "The presence of soluble BAG6/BAT3 (another NKp30-L) in the plasma of chronic lymphocytic leukemia patients was found to correlate with advanced disease stages." (PMID 31316503, 2019). "It should be noted that a soluble form of BAG6 (sBAG6) in the plasma of chronic lymphocytic leukaemia patients critically impaired the function of NK cells, whereas vesicular BAG6 is a powerful activator of NK cells." (PMID 29158311, 2018). "By contrast, exosomes carrying BAG6, another NKp30 ligand, are necessary to activate NK cells in order to eliminate chronic lymphocytic leukemia (CLL) cells, whereas soluble BAG6 lead to tumor evasion." (PMID 27014273, 2016). "Furthermore, soluble ligand BAG6/BAT3 was found to exist in chronic lymphocytic leukemia patients’ blood." (PMID 36405712, 2022).
non-small cell lung carcinoma (5 papers, 2012 to 2025). A group of at least three distinct histological types of lung cancer, including non-small cell squamous cell carcinoma, adenocarcinoma, and large cell carcinoma. "Logistic regression analyses revealed that genotypes and alleles of BAG6 were independent predictive factor for non small cell lung cancer risk in the Norwegian and combined Croatian-Norwegian subjects, after adjustment for age and gender." (PMID 25884493, 2015). "Together these results suggest that RAB3A mediates the transport of BAG6 to mitochondria, thereby optimizing the therapeutic potential of cisplatin for non-small cell lung cancer treatment." (PMID 41123819, 2025). "Our results support these previous reports and further suggest a role for the BAG6 gene in the etiology of non small cell lung cancer." (PMID 25884493, 2015).
asthma (4 papers, 2018 to 2024). "With respect to increased risk of asthma, blood genes again had the largest relative effect sizes in males (BAG6, CCNG, CRAT, PTPA, and FAM89B), with female training genes exhibiting the largest effects in ATP6V1G2 in the vastus lateralis, ENDOU in white adipose, and CCNF in blood." (PMID 38693125, 2024).
colon carcinoma (3 papers, 2012 to 2019).
colorectal cancer (3 papers, 2023 to 2024). A primary or metastatic malignant neoplasm that affects the colon or rectum. "Notably, BAG6 has been implicated in driving colorectal cancer progression as a nucleocytoplasmic shuttling protein." (PMID 37815698, 2024). "Previous studies have reported the chemotherapy resistance of BAG6 in breast cancer and colorectal cancer." (PMID 37815698, 2024). "We provided a template for such analyses by elucidating the potential role of BAG6 colorectal cancer pathogenesis and prognosis." (PMID 38608194, 2024). "KCTD5 has been identified as having a role in cell migration 28, 29; and GET4, as part of a larger protein complex with BAG6, has been shown to play a role in the recruitment of BRCA1 to sites of DNA damage 30 and promote tumour growth in models of colorectal cancer." (PMID 37771787, 2023).
Infertility (3 papers, 2020 to 2025). "Therefore, the downregulation of HSPA2, BAG6, and SPA17 in the present study indicates that sperm and oocyte recognition may be associated with the abnormal sperm linked with infertility." (PMID 34213690, 2021).
pancreatic cancer (3 papers, 2019 to 2024). "The aim of the study was to investigate the role of the immune cell regulator and chaperone BAG6 (Bcl2-associated-athanogene 6) in EV cargo loading and function within the pancreatic cancer TME." (PMID 39811732, 2024). "Addressing a putative role of the chaperone BAG6 in pancreatic cancer (PC) we measured the BAG6 protein level in plasma samples of PC patients (quantified using Olink Explore 3072 analysis)." (PMID 38942797, 2024).
virus Infection (3 papers, 2022 to 2024). "The aggregation of VISA and the interaction of VISA and TRAF2 are enhanced in BAG6-deficient cell lines after viral infection, resulting in the enhanced transcription level of downstream antiviral genes." (PMID 36045679, 2022). "BAG6 facilitated the K48-linked ubiquitination of VISA may lead to inhibition of signal transduction by a failure of VISA to aggregate normally after virus Infection." (PMID 36045679, 2022). "This BAG6-associated fraction of MAVS is dynamic and responds to the activation of an innate immune response, suggesting that BAG6 may modulate the pool of MAVS that is available for coordinating the cellular response to viral infection." (PMID 35543156, 2022). "Further studies will be required to establish whether this BAG6-bound pool of MAVS plays any specific role in the propagation of RIG-I-like receptor-dependent signalling following viral infection." (PMID 35543156, 2022). "However, the role of BAG6 in virus infection remains opaque." (PMID 38498560, 2024). "The successful depletion of BAG6 in lung by BAG6-targeting PPMO (PPMO-BAG6) was confirmed by western blotting compared with PPMO control (PPMO-NC) before and after virus infection." (PMID 38498560, 2024). "Due to the potent antiviral activity of BAG6, we next determined whether IAV was able to regulate BAG6 expression during virus infection to evade its antiviral effects." (PMID 38498560, 2024). "No obvious effects on either the phosphorylation or dimerisation of IRF3 were detected following knockdown of the Bag6 protein, suggesting that the BAG6 complex is not an essential component for the cellular mobilisation of a MAVS-dependent response to viral infection." (PMID 35543156, 2022). "However, the role of BAG6 in virus infection has not been explored." (PMID 38498560, 2024).